ENSG00000252798
Gene: Small Cajal body-specific RNA gene on chromosome 16 (21,587,627 to 21,587,864, forward strand). Ensembl gene ENSG00000252798.
Gene Ontology:
Biological process: RNA processing
Cellular component: nucleolus